PTX3 (pentraxin 3)
Diseases named in the same sentence as PTX3 in open-access papers (continued):
Sharing a sentence is not in itself a finding about the gene and the disease.
breast carcinoma (continued). "PTX3 interacts with the PI3K/AKT/mTOR signaling pathway to induce tumor cell proliferation, apoptosis and metastasis in lung cancer, head and neck squamous cell carcinoma and breast cancer." (PMID 33013829, 2020). "This evidence suggests that Nav 1.5 functional activities may play a role in PTX3 expression in breast cancer, through which rBmK AGAP mediate down-regulation of PTX3 via NF-κB signaling pathway." (PMID 30740360, 2019). "Accordingly, transgenic PTX3 overexpression by tumor cells efficaciously impairs the activation of the FGF/FGFR system in FGF-driven tumor cell lines, thus affecting tumor growth and metastasis in different models of melanoma, prostate and mammary carcinomas." (PMID 30443492, 2018). "Moreover, PTX3 inhibits the FGF-induced mitogenic, angiogenic, and tumorigenic potential in steroid hormones-regulated tumors, prostate cancer cells and breast cancer." (PMID 28489600, 2017). "In addition, PTX3 is a CCAAT/Enhancer Binding Protein Delta -responsive gene and serves a protumor role in breast cancer cells upon anticancer drug treatment." (PMID 28489600, 2017). "High PTX3 level was significantly correlated with a distant metastasis to bone compared to non-bone tissues of breast cancer (GSE14020)." (PMID 24457902, 2014). "In this study, TNFα treatment led to significant over-expression of PTX3 in bone metastatic breast cancer cells, but not in non-bone metastatic breast cancer cells, reinforcing PTX3 as a modulator of breast cancer-related inflammation." (PMID 24457902, 2014). "PTX3 mRNA expression was significantly increased in the bone metastatic breast cancer cell line MDA-MB-231 compared to the non-bone metastatic breast cancer cell line MCF-7, as shown by RT-PCR." (PMID 24457902, 2014). "A significant up-regulation of PTX3 expression in bone metastasized tumor tissues was detected compared to non-bone metastasized tumor tissues in breast cancer patients." (PMID 24457902, 2014). "Analysis of PTX3 expression between bone metastatic and non-bone metastatic relapsed malignant tissues from breast cancer patients was performed using published data from the Gene Expression Omnibus (GEO)." (PMID 24457902, 2014). "We addressed the elevated expression and secretion of PTX3 in breast cancer cells with bone metastatic properties compared to non-bone metastases of breast cancer, and its related regulation by TNFα." (PMID 24457902, 2014). "In basal-like and HER2-positive breast cancers, we demonstrated that a low WWOX/HIF1A ratio is particularly detrimental, as it triggers HIF1α-mediated upregulation of immunosuppressive mediators such as TLR4, NOTCH1, PTX3, and IL6R, alongside glycolytic enzymes like GLUT1 and HK2." (PMID 41007296, 2025). "On the other hand, in prostate cancer cell lines, higher levels of PTX-3 were expressed by non-bone metastatic cells, probably due to more frequent osteoblastic cellular activity rather than osteolytic activity (encountered in breast cancer cell lines)." (PMID 36499628, 2022). "In addition, all of the biochemical parameters we analysed were statistically significant in both breast cancer patients (NF-κB: p<0.001; sTRAIL: p<0.01; TNF-α: p<0.001; IL-6: p<0.001; PCT: p<0.001; PTX-3: p<0.001; CRP: p<0.001) and colon cancer patients (for all p<0.001) compared to the control." (PMID 33776564, 2021). "These seemingly contradictory observations could be reconciled by the fact that PTX3 was highly expressed only in CSC subpopulation of breast cancer and was nearly undetectable in non-CSCs." (PMID 32427938, 2020). "To understand better the mechanism by which TNFα increases PTX3 production in breast cancer cells, we examined the effects of inhibitors of extracellular signal-regulated protein kinase (ERK), p38 mitogen-activated protein kinase (MAPK), JNK, or NF-κB on PTX3 expression." (PMID 24457902, 2014).
breast carcinoma (continued). "We found that high levels of PTX3 mRNA and protein were expressed in the non-bone metastatic prostate cancer cell line DU-145 compared to bone metastatic prostate cancer cell line PC-3, in contrast to breast cancer cells." (PMID 24457902, 2014). "It should be noted that either TNFα or PTX3 treatment did not influence RANKT expression in breast cancer cells themselves (data not shown), indicating that PTX3 might be involved in OC formation indirectly." (PMID 24457902, 2014). "From the upregulated genes of the EMT-core gene list, high PTX3 expression tends to poor overall survival of SCC patients (p = 0.16) and high expression of NID2 (p = 0.0091), SPOCK1 (p = 0.038) and SULF1 (p = 0.00029) significantly correlated with impaired pCR of breast cancer patients." (PMID 23251436, 2012). "Having shown that MDA-MB-231 cells produce elevated levels of PTX3 compared to MCF-7 cells, we questioned whether PTX3 produced by MDA-MB-231 cells could induce chemotactic migration of macrophages toward breast cancer cells and subsequently enhance osteoclastogenesis." (PMID 24457902, 2014). "PTX3 silencing in MDA-MB-231 cells transfected with PTX3 siRNA significantly decreased TNF-α-mediated RANKL production in the co-culture system, but did not modulate OPG production, supporting the notion that PTX3 may serve as an inflammatory mediator involved in breast cancer-related osteolysis." (PMID 24457902, 2014).
Obesity (52 papers, 2009 to 2025). Accumulation of substantial excess body fat. "In healthy individuals, PTX3 levels are typically low but are associated with metabolic syndrome, insulin resistance, muscle mass, and obesity-related indicators, including BMI, waist-hip ratio, and visceral fat mass." (PMID 41562853, 2025). "The long pentraxin 3 (PTX3), a marker of inflammation, has been associated with cardiovascular disease, obesity, and metabolic syndrome." (PMID 39657836, 2025). "Obesity has been linked to reduced plasma levels of PTX3 protein but concurrently increased PTX3 gene expression in adipose tissue." (PMID 39594709, 2024). "Following the purpose of the study, patients with the obesity–periodontitis association had significantly higher levels of PTX3 and SAA than those with one of the diseases or healthy individuals, and these values correlated with certain clinical parameters." (PMID 37240630, 2023). "PTX3 has been reported to be associated with adipose tissue and obesity in a genetic mouse model of obesity." (PMID 34035808, 2021). "Our study also confirmed that PTX3 can increase the susceptibility to obesity by regulating the expression of adipogenic markers; this regulatory role of PTX3 is most likely caused by MAPK pathway hyperactivation." (PMID 28770376, 2017). "In other words, PTX3 can increase the susceptibility to obesity by regulating the expression of adipogenic markers." (PMID 28770376, 2017). "We found an association of PTX-3 with risk factors such as obesity, uric acid, LDL-C, hsCRP, RBP-4 and adiponectin." (PMID 28977161, 2017). "Circulating PTX3 concentrations are negatively associated with numerous indices of obesity, including BMI, waist and hip circumferences, and visceral fat mass, and positively associated with muscle mass." (PMID 28400677, 2017). "To probe further the association of PTX3 and obesity, we stratified the control subjects by diabetic status." (PMID 24705587, 2014). "Consistent with the impact of obesity and waist circumference on PTX3, plasma PTX3 was associated negatively with BMI and WC, and both associations were independent of age and plasma creatinine in multiple regression analysis." (PMID 24215445, 2013). "Obesity is a risk factor for cardiovascular disease and PTX3 production is reported in abdominal adipose tissue." (PMID 24215445, 2013). "Obesity causes low-grade inflammation mostly due to adipocytes and immune cells secreting proinflammatory molecules such astumor necrosis factor receptors 1 and 2, PTX3, and Il15." (PMID 37240630, 2023). "In this article we discuss whether inflammation will directly lead to obesity, Our study confirmed that PTX3 is most likely caused by MAPK pathway hyperactivation can increase the susceptibility to obesity by regulating the expression of adipogenic markers." (PMID 28770376, 2017). "The current findings however indicate a novel link between obesity and plasma PTX3 in ACS, and understanding the underlying mechanisms will likely lead to novel potential prevention and treatment strategies to improve ACS prognosis in both obese and non-obese patients." (PMID 24215445, 2013). "Therefore, PTX3 plays an important role in increasing obesity susceptibility." (PMID 28770376, 2017). "However, the activity of PTX3 and the specific mechanisms in that intrauterine inflammation causes offspring mouse obesity remain unknown." (PMID 28770376, 2017). "Furthermore, plasma PTX3 levels are inversely associated with body mass index (BMI) suggesting that PTX3 may play a role in obesity and metabolic syndrome." (PMID 24350299, 2013). "It has been suggested that PTX-3 is a link between obesity, inflammation, and metabolic and cardiovascular complications of obesity." (PMID 40066165, 2025). "PTX3 helps regulate inflammation in obesity by counteracting pro-inflammatory cytokines like IL-6 and TNF-α." (PMID 41562853, 2025).
Obesity (continued). "In a population of adolescents with obesity, PTX-3 concentrations above 3.03 ng/mL were shown to distinguish between fatty liver and NASH, with 89% sensitivity and 86% specificity." (PMID 40066165, 2025). "In contrast, our study identified that, within the PreDM group, PTX3 values were found to be statistically significant and positively correlated with BMI and various obesity-related indices, including weight and WHR." (PMID 40332236, 2025). "Contrary to results obtained in the middle-aged population (sensitivity 91.1% and specificity 71.4% for PTX-3 cutoff of 2.45 ng/mL) and adolescents with obesity (sensitivity 89.0% and specificity 86.0% for PTX-3 cutoff of 3.03 ng/mL)." (PMID 40066165, 2025). "Although biomarkers such as 8-OHdG, IL-8, resistin, TNFR1, PTX-3, and sICAM-1 are closely associated with MUO and metabolic disorders, they have not yet been established as primary diagnostic biomarkers for obesity-tests in clinical practice." (PMID 40153192, 2025). "Our study shows a strong link between PTX3 values and obesity, suggesting PTX3 as a potential biomarker for early diabetes diagnosis." (PMID 40332236, 2025). "PTX3, an acute phase response protein, plays an anti-inflammatory role in obesity-related inflammation (Slusher, Huang & Acevedo, 2017)." (PMID 39372725, 2024). "Elevated PTX3 was reported in subjects with obesity and was correlated with a higher frequency of metabolic syndrome and more hepatic steatosis." (PMID 39296904, 2024). "Univariate regression analysis showed that hypertension (OR 15.2), diabetes (OR 7.05), and obesity (OR 4.14) are the most significant predictors of CXR infiltrate severity, together with ACE D/D polymorphism (OR 3.58) and PTX3 serum level (OR 1.26)." (PMID 39062191, 2024). "In the context of obesity, the expression of PTX3 in preadipocytes within VAT has been observed to be rare." (PMID 38111581, 2023). "Some research interest has been driven toward the study of plasma pentraxin 3 (PTX3), which represents an acute-phase protein belonging to the PTX family, significantly associated with obesity, metabolic syndrome, and cardiovascular diseases." (PMID 37999211, 2023). "The same investigators demonstrated 5 years later that increased serum levels of PTX3 positively correlate with age, obesity, systolic blood pressure, serum CRP levels, or carotid intima-media thickness (p values below 0.045 for all parameters)." (PMID 35563387, 2022). "Pentraxin 3 (PTX3) - a crucial humoral innate immunity component – is related to obesity and cardiovascular complications in women who suffer from polycystic ovary syndrome (PCOS)." (PMID 34856980, 2021). "It was reported that PTX3 mRNA expression is upregulated in visceral adipose tissue in obesity, whereas the plasma PTX3 levels inversely correlated with insulin secretion." (PMID 33594624, 2021). "Unexpectedly, the increasing degree of obesity, insulin resistance, and inflammation (reflected by MCP-1 and IL-6 levels) in PCOS was associated with increased PTX3 production." (PMID 32934654, 2020). "PTX3 is also less influenced by total cholesterol, high-density lipoprotein, hemoglobin, smoking, obesity or gender." (PMID 31703088, 2019). "PTX3 also has an inverse relationship with the development of obesity, as the plasma PTX3 concentration has been reported to significantly decrease with an increasing BMI22." (PMID 31147578, 2019). "Serum PTX3 level was correlated with insulin resistance in patients with obesity or polycystic ovary syndrome." (PMID 29715313, 2018). "Plasma long pentraxin 3 (PTX3) was reported to be associated with type 2 diabetes, human obesity, and metabolic syndrome." (PMID 30422989, 2018). "For example, serum PTX3 level was negatively correlated with baPWV in patients with obesity and GDM." (PMID 29715313, 2018).
Obesity (continued). "Counter to obesity-related inflammation, pentraxin 3 (PTX3) is an acute-phase protein that is induced in response to proinflammatory stimulation by a variety of cell types, including adipocytes, neutrophils, monocytes, and macrophages." (PMID 28400677, 2017). "We determined that PTX3 was an important moderator of obesity, and we elucidated its mechanism, thus providing new targets and theories for obesity therapy." (PMID 28770376, 2017). "High expression of PTX3 promotes the formation of adipocytes through the regulation of differentiation marker expression, and it eventually leads to obesity." (PMID 28770376, 2017). "All of these studies indicate that PTX3 plays an important role in the development and progression of obesity." (PMID 28770376, 2017). "This study has shown that prenatal exposure to LPS will lead to obesity and that PTX3 plays an important regulatory role in obesity." (PMID 28770376, 2017). "With obesity, PTX3 mRNA expression is elevated in adipose tissue and is positively associated with the mRNA expression of the proinflammatory cytokines interleukin-1 beta (IL-1β) and tumor necrosis factor alpha (TNF-α)." (PMID 28400677, 2017). "Although the precise mechanisms are still unclear, elevated PTX-3, RBP-4, IL-33, irisin and decreased adiponectin levels increase the risk of obesity-related metabolic disorders." (PMID 28977161, 2017). "In a previous study using an obesity-induced inflammation model, overexpression of PTX3 regulated the cell uptake of OX-LDL to prevent the outflow of cholesterol through activation of the ERK1/2 pathway." (PMID 28770376, 2017). "The negative correlation between BMI and PTX3 levels during pregnancy and at 5-year follow-up supports recent studies demonstrating low PTX3 levels in patients with the metabolic syndrome and obesity." (PMID 26842615, 2016). "Whereas plasma levels of the short pentraxin CRP are higher in obese individuals and those with metabolic syndrome, evidence linking PTX3 with obesity and metabolic syndrome remains scant." (PMID 24705587, 2014). "The present study using MI survivors, and another clinical study in a healthy Japanese population, found that PTX3 is inversely correlated with obesity and metabolic syndrome." (PMID 24705587, 2014). "PTX3 values were significantly high in patients with obesity (body mass index (BMI) ≥ 30), cardiovascular diseases, and continuous systemic cortisone treatment (daily dose over 10 mg oral prednisolone) compared to those without these risk factors." (PMID 25530683, 2014). "The potential interaction between obesity, PTX3 and ACS outcome and survival will also need to be investigated and confirmed in future studies." (PMID 24215445, 2013). "We investigated the potential impact of obesity and high waist circumference (reflecting abdominal fat accumulation) on plasma PTX3 concentration in ACS patients (n = 72, 20 obese) compared to age-, sex- and BMI-matched non-ACS individuals." (PMID 24215445, 2013). "In the current study we provide novel information on the impact of obesity or waist circumference on plasma PTX3 in ACS." (PMID 24215445, 2013). "As with the short pentraxin CRP, PTX3, a member of the long pentraxin family, has been suggested to comprise a mechanistic link between chronic low-level inflammation and obesity." (PMID 22509348, 2012). "Obesity and high SOFA score (≥4) also remained independent factors associated with case fatality when studied together with high PTX3." (PMID 21423699, 2011). "However, the increase in PTX3 levels following acute aerobic exercise appears to be similar across individuals with normal weight, overweight, and obesity." (PMID 41562853, 2025). "Although lipocalin-2, pentraxin-3, and osteoprotegerin are generally considered pro-inflammatory or obesity-related, their elevation in the FIP + Fat group may reflect regulatory or tissue-protective roles in certain settings." (PMID 40998975, 2025).